ENSG00000200113
Synonyms: LOC124900242
Gene: Small nucleolar RNA gene on chromosome 7 (37,419,628 to 37,419,767, forward strand). Ensembl gene ENSG00000200113.
Gene Ontology:
Biological process: RNA processing
Cellular component: nucleolus
Homologues: Paralogues in human: SNORA51 (82% identical).